PLP1 (proteolipid protein 1)
Diseases named in the same sentence as PLP1 in open-access papers (continued):
Sharing a sentence is not in itself a finding about the gene and the disease.
schizophrenia (9 papers, 2010 to 2023). A major psychotic disorder characterized by abnormalities in the perception or expression of reality. "There is also evidence for a genetic association of PLP1 with schizophrenia." (PMID 22937274, 2011). "Some of these genes have been genetically associated with schizophrenia, namely neuroplastin (Nptn/Sdfr1), numb homolog (Drosophila)-like (Numbl), proteolipid protein 1 (Plp1), gamma-aminobutyric acid (GABA) A receptor, α1 (Gabra1), and reticulon 4 (Rtn4/(NogoA)." (PMID 21629445, 2010). "Furthermore, the PLP1 gene is thought to be associated with schizophrenia in mice and human." (PMID 30728412, 2019). "Lower levels of PLP1 mRNA have been reported in schizophrenia." (PMID 22937274, 2011). "These abnormal behaviors are schizophrenia-related behaviors, suggesting that the plp1tg/− mice may be used as a potential animal model to examine the role of altered plp1 gene in schizophrenia." (PMID 22937274, 2011). "The association of a myelination-related module with schizophrenia is in line with a wide range of reported white matter abnormalities linked to the illness and genetic studies that have contributed a number of myelin and oligodendrocyte –related genes as candidate genes (e.g. APOD, PLP1, MAG)." (PMID 24070017, 2013). "The study analysing gene-miRNA interaction network identified miRNAs (miR-92a, miR-495, miR-134) directly regulating gene expression by the binding site in BCL11 A, PLP1 and SYT11, which are changed in the PFC in patients with schizophrenia." (PMID 36833173, 2023). "Moreover, the downregulation of myelin-related and oligodendrocyte genes such as proteolipid protein 1 (PLP1), transferrin (TF), oligodendrocyte transcription factor 1 (OLIG1), and upregulation of myelin basic protein (MBP) were reported in the PFC of patients with schizophrenia." (PMID 36833173, 2023).
Anxiety (8 papers, 2013 to 2025). Intense feelings of nervousness, tension, or panic often arise in response to interpersonal stresses. "Collectively, the downregulation of CRYAB, CCK, and PLP1 appears to play a critical role in the cognitive impairment and anxiety-like behavior observed in anosmic mice in the present study." (PMID 40673140, 2025). "In rats, the overexpression of the myelin transcription factor 1 (MyT1) promotes differentiation of oligodendrocytes, which is also regulated by Plp1 and Mbp, and ameliorates anxiety-like and compulsive behaviors." (PMID 35326487, 2022). "Genetic manipulation of several oligodendrocyte-related genes, such as Cnp1 and Plp1, led to altered anxiety-related behaviors." (PMID 29379874, 2017). "Paradoxical results in the evaluation of anxiety-like behavior have been previously observed in mice overexpressing PLP1, indicating myelin impairments could disrupt emotional regulation." (PMID 29436368, 2018). "Behavioral characterization of anxiety-like behavior in Plp1-null mice." (PMID 29436368, 2018). "Plp1-OE in oligodendrocytes did not alter anxiety-like behavior in the elevated plus maze (EPM) or total activity in the open field in either XY or XX mice." (PMID 40043106, 2025).
colitis (7 papers, 2017 to 2024). Inflammation of the colon. "In line, we observed an increase in S100β expression in PLP1-positive cells within the myenteric plexuses of DNBS rats that persisted until day 7 from colitis induction." (PMID 34829900, 2021). "Here we present evidence that enteric cells expressing Sox2 and PLP1, markers that label enteric glia in the adult gut, undergo neurogenesis in response to colitis." (PMID 28566702, 2017). "Given recent work on the neurogenic potential of EGCs52,59, it is notable that we saw upregulation of the canonical glial markers GFAP and S100β specifically in cured mice, as well as PLP1, which corresponds to the subset of glial cells that differentiate into neurons in the DSS colitis model." (PMID 38782898, 2024). "Indeed, DSS-induced colitis was shown to trigger the transdifferentiation of SOX2+, PLP1+ glial cells to enteric neurons." (PMID 34571902, 2021). "To determine whether PLP1-expressing cells are capable of undergoing neurogenesis in vivo, we subjected adult mice (>4 months old) to DSS colitis." (PMID 28566702, 2017). "Similarly in PLP1CreER:tdT mice, PLP1 cells that co-express S100b but not RET also give rise to neurons following colitis." (PMID 28566702, 2017).
experimental autoimmune encephalomyelitis (7 papers, 2012 to 2025). An autoimmune demyelinating disease of the central nervous system that is produced experimentally in animals by the injection of homogenized brain or spinal cord in Freund's adjuvant. "In this tissue we noted that Plp1, for which incomplete thymic splicing can contribute to experimental autoimmune encephalomyelitis (EAE), had significantly higher numbers of splice junctions in the periphery." (PMID 34649931, 2021).
glioma (7 papers, 2018 to 2026). A benign or malignant brain and spinal cord tumor that arises from glial cells (astrocytes, oligodendrocytes, ependymal cells). "The genes AQP4, BCAN, GFAP, PLP1, and S100B are part of the astrocytic, oligodendrocytic, or proneural glioma signatures." (PMID 34101353, 2021). "Our results demonstrate brain tissue-specific proteins such as GFAP and PLP1 to be present in both TiMas and subsets of blood monocytes, especially in diseases with brain tissue-damage such as glioma, brain metastases and AIS." (PMID 33501422, 2021). "The TRPV2 interactome showed a high association with early glia-related neoplasms, especially glioma/glioblastoma, being ABR, FGF1, KCNJ10, PEBP1, PLP1, SDC3, and TRPV2, the genes associated to these brain neoplasms." (PMID 29719613, 2018). "The myelin-specific proteolipid protein (PLP1) and glioma-specific mutated proteins EGFRvIII and IDH1R132H, have not been found in serum but are other highly tissue- or tumour-specific proteins." (PMID 33501422, 2021). "The expression of PLP1, a predominant component of myelin, is correlated with the percentage of the oligodendroglioma component in gliomas and down-regulation/loss of the ABR tumor suppressor gene was found in gliomas and medulloblastoma." (PMID 30845786, 2019). "PLP1, FTH1, and GM42418 were validated as potential molecular biomarkers, providing novel insights into glioma pathogenesis and potential therapeutic targets." (PMID 42283031, 2026).
Cognitive impairment (6 papers, 2016 to 2025). Abnormal cognition is characterized by deficits in thinking, reasoning, or remembering. "Patients with mutations resulting in complete deletion of the PLP1 protein exhibit mild early impairments that progress to spastic quadriplegia, ataxia, and cognitive impairments in adolescence." (PMID 29436368, 2018). "Severe cognitive impairment occurred in patients with mutations in NKX6-2, PLP1, PAH gene (when untreated), and SCN2A (in early-onset type), whereas milder ID was associated with SCN2A (in late-onset type) or SMAD6 variants." (PMID 41300846, 2025). "While Plp1-null mice appear grossly normal, and learning and memory are relatively unaltered, cognitive impairments requiring higher-order processing were observed, which became increasingly apparent with task difficulty in the Puzzle Box." (PMID 29436368, 2018). "In addition, we observed some downregulated genes (such as MPZ, GJB1, CDH15, KCNQ3, and PLP1) in K-NSC cells, and abnormal expression of these genes has been reported to cause cognitive impairment, epilepsy, spasticity, and myelin abnormalities, which are similar to the disease symptoms of GLD." (PMID 37076788, 2023).
melanoma (6 papers, 2008 to 2025). A malignant, usually aggressive tumor composed of atypical, neoplastic melanocytes. "Specifically within tumor samples, we observed an abundant cell type that expressed markers commonly seen in melanoma, including the markers Plp1, Gpm6b, Postn, Mcam, S100b35." (PMID 40571713, 2025). "We also looked up various genes classically expressed by Schwann cell precursors or Schwann cells and found that Gap43, Fabp7, Mpz, Dhh, Ngfr, Ncam1, and Mbp were all significantly upregulated in the sparse pigment tumors than in the intradermal melanomas, as was Plp1." (PMID 39804140, 2025). "Histologically, tumors from Plp1::CreERT2; BrafCA/+; Ptenlox/+ animals were indistinguishable from their Ptenlox/lox counterparts, including the extensive infiltration of non-traced (tdTomato− and/or Sox10−) stromal cells, which was markedly higher compared to melanoma samples." (PMID 41063628, 2025). "In contrast to melanomas derived from Tyr::CreERT2; BrafCA/+; Ptenlox/lox mice, histological analysis of Plp1::CreERT2; BrafCA/+; Ptenlox/lox tumors revealed no signs of pigmentation at the microscopic level." (PMID 41063628, 2025). "In addition, we identified Mesenchyme (COL1A1+), Endothelium (SOX18+, KDR+), proliferating cells (TOP2A+, MKI67+), and some off‐target cells; Glial (MSX1+, SOX2+), Melanoma (PMEL+, PLP1+), and Neuron (DLL3, HES6)." (PMID 35322595, 2022). "Interestingly, this includes many genes that we found commonly regulated between fish and human melanoma (e.g. BCL2, WNT family members) or which became evident in the fish tumor comparisons, e.g. components of the ECM, cell cycle regulators, PLP1, and CLIC3." (PMID 22693581, 2012). "The other two genes from the Met library (PLP-1 and HLA-DRA) did not exhibit expression pattern clearly associated to any specific stage of the melanoma progression in this study (bottom)." (PMID 18211678, 2008). "Likewise, Tyr::CreERT2 - driven Ezh2 GOF, which results in canonical Wnt signal activation in the melanocyte lineage, promotes melanoma formation, whereas Plp1::CreERT2 -driven Ezh2 GOF in MPNSTs had no overt effect on the tumor phenotype." (PMID 41063628, 2025).
Nystagmus (6 papers, 2011 to 2025). Rhythmic, involuntary oscillations of one or both eyes related to abnormality in fixation, conjugate gaze, or vestibular mechanisms. "Patients with the most common classic PMD presentation, mainly caused by PLP1 duplications, typically demonstrate onset of nystagmus during infancy, delayed motor development with axial hypotonia, progressive spasticity, and cerebellar signs." (PMID 41315317, 2025). "PMD caused by PLP1 mutations is characterized by developmental delay, nystagmus, hypotonia and other neurological symptoms." (PMID 35346287, 2022). "The patients who harbored F240L displayed a severe phenotype in group A. There also was one female with a de novo PLP1 deletion (Pt4), she acquired head control at 17 months, and concomitant symptoms of nystagmus and hypotonia were also diagnosed." (PMID 35346287, 2022). "Patients experienced psychomotor delay or nystagmus in the first year of age and then developed ataxic–spastic or ataxic syndrome, compatible with a phenotype of intermediate severity in the spectrum of PLP1-related disorders." (PMID 33450882, 2021).
Alzheimer disease (5 papers, 2014 to 2025). A progressive, neurodegenerative disease characterized by loss of function and death of nerve cells in several areas of the brain leading to loss of cognitive function such as memory and language. "We further focused on predicting key genes in neuroscience studies, including 4 genes with differential spatial and cellular expression (Kcnma1, Plp1, Ptgds, and Ttr), as well as the Alzheimer’s disease-related gene Apoe." (PMID 41210658, 2025). "Two-way ANOVA revealed a highly significant interaction effect between infection and dementia status for MAG:PLP1 in both Alzheimer’s disease and vascular dementia patients." (PMID 33723589, 2021). "The MAG:PLP1 ratio was highly significantly reduced in Alzheimer’s disease and vascular dementia patients compared to age-matched controls." (PMID 33723589, 2021). "Here, we show that MAG:PLP1 and PDGFRβ were significantly reduced, at an early stage i.e. BSIII–IV, in Alzheimer’s disease indicating vascular dysfunction from an early to intermediate stage of disease." (PMID 33723589, 2021). "In a combined Alzheimer’s disease and control group, MAG:PLP1 was significantly reduced in BSIII–IV and BSV–VI compared to BS0–II." (PMID 33723589, 2021). "White matter ACE activity did not correlate significantly with the MAG:PLP1 ratio and was similar in Alzheimer’s disease, vascular dementia and controls." (PMID 24618270, 2014). "One-way ANOVA, to assess differences between control and disease groups after stratification according to the presence of infection, showed MAG:PLP1 to be reduced in controls with infection to a level comparable to that in Alzheimer’s disease or vascular dementia patients without infection." (PMID 33723589, 2021). "In all dementia cases (i.e. combining Alzheimer’s disease, mixed and vascular dementia) but not controls, MAG:PLP1 in the FC correlated positively with DBP (Pearson’s r = 0.1985, P = 0.0259, n = 126) and PC (r = 0.1971, P = 0.0282, n = 124) but not with SBP." (PMID 37113314, 2023). "Indeed, in cases with no or minimal Alzheimer’s disease pathology (BS0–II), MAG:PLP1 declined and VEGF and fibrinogen increased by magnitudes similar to those in end-stage Alzheimer’s disease in control donors with terminal infection." (PMID 33723589, 2021).
dementia (5 papers, 2014 to 2023). Loss of intellectual abilities interfering with an individual's social and occupational functions. "VEGF concentration correlated negatively with the MAG:PLP1 ratio in both the South West Dementia Brain Bank cohort (r = −0.315, P = 0.0015) and the Oxford cohort (r = −0.631, P < 0.0001)." (PMID 24618270, 2014).
demyelinating disease (5 papers, 2013 to 2025). A broad group of disorders that affect the myelin sheaths that cover the neurons. "It is a major structural component of myelin, and deficiency or dysregulation of PLP1 expression has been implicated in several neurodegenerative and demyelinating diseases, like hereditary spastic paraplegias, which always accompanying with neuroinflammation and immunodeficiencies." (PMID 41303439, 2025). "PLP is critically important to myelin biosynthesis, structure, and function, as evidenced by the very high degree of PLP1 gene sequence conservation (human and mouse genes are identical) and the severity of the X-linked demyelinating diseases observed in PLP1 mutant individuals." (PMID 32528735, 2020). "Thus, the methods to ameliorate inflammation and enhance immunity by up-regulating PLP1 expression might play roles in treating neurodegenerative and demyelinating diseases." (PMID 41303439, 2025). "A demyelination disorder mouse model named “jimpy” is similar to human PMD, With a lack of 208–232 amino acid regions in jimpy mouse, PLP1 dysfunction and oligodendrocyte cell death were observed." (PMID 35346287, 2022).
glioblastoma (5 papers, 2015 to 2024). The most malignant astrocytic tumor (WHO grade IV). "Functional involvement of PLP1 in thyroid cancer is virtually unknown; however, in glioblastoma multiforme, PLP1 expression correlated with the extent of the oligodendroma component." (PMID 25923053, 2015). "We validated the regional expression of PLP1 and DNM1 by analyzing their RNA expression in the Ivy Glioblastoma Atlas Project database." (PMID 32642662, 2019).
hereditary spastic paraplegia (5 papers, 2018 to 2025). Hereditary spastic paraplegias (HSP) comprise a genetically and clinically heterogeneous group of neurodegenerative disorders characterized by progressive spasticity and hyperreflexia of the lower limbs. "Spastic paraplegia type 2 (SPG2) is an X‐linked recessive (XLR) form of hereditary spastic paraplegia (HSP) caused by mutations in proteolipid protein 1 (PLP1) gene." (PMID 36622199, 2023). "Axon degeneration is also the cause of progressive spasticity in the corresponding human PLP1 null patients with SPG2; belonging to the family of disorders termed the hereditary spastic paraplegias." (PMID 30050403, 2018).
Intellectual disability (5 papers, 2016 to 2025). "Most of the CNVs in this interval include PLP1 and neighboring genes, suggesting the occurrence of microdeletion and microduplication syndromes at Xq22.2 with phenotypic features including intellectual disability (ID), behavioral abnormalities, and hypotonia." (PMID 27506666, 2016). "Among the 21 annotated genes at Xq22.2, PLP1 is the only known gene involved in Xq22.2 microdeletion and microduplication syndromes with intellectual disability." (PMID 27506666, 2016). "Indeed, female carriers with a gross deletion in PLP1 are likely to present with EONDT (severe developmental delay, intellectual disability, and behavioral abnormalities)." (PMID 36622199, 2023). "Using an atypical microdeletion, which does not encompass PLP1, we implicate a novel gene GLRA4 involved in intellectual disability, behavioral problems and craniofacial anomalies." (PMID 27506666, 2016).
Spastic paraplegia (4 papers, 2013 to 2022). Complete loss of the ability to move the lower limbs accompanied by spasticity of the lower limbs. "In the top 5 quantiles of the green module, we found genes associated with spastic paraplegia (PLP1-OMIM#300401), Niemann-Pick disease (NPC1-OMIM#607623), and Canavan disease (ASPA-OMIM#271900)." (PMID 26707700, 2016). "In humans, mutations in the PLP1 gene cause a spectrum of neurological diseases that vary in severity from the milder spastic paraplegia (SPG2) to the severe connatal Pelizaeus-Merzbacher disease (PMD)." (PMID 24314267, 2013). "Like PLP1, most patients have onset of symptoms in early life, but there are reports of later onset with slow progression into adulthood, again mostly manifesting by spastic paraplegia, cerebellar signs and a hypomyelinating picture on MRI." (PMID 30467211, 2019).
developmental delay (3 papers, 2022 to 2024). "The patient exhibited developmental delay but no hypomyelination despite PLP1 involvement in the deletion." (PMID 38750072, 2024).
leiomyoma (3 papers, 2008 to 2023). A well-circumscribed benign smooth muscle neoplasm characterized by the presence of spindle cells with cigar-shaped nuclei, interlacing fascicles, and a whorled pattern. "PLP1 was considered as the hypomethylation and transcriptionally upregulated genes in leiomyoma based on the genome-wide DNA methylation and mRNA expression analysis." (PMID 36386836, 2022).
autism (2 papers, 2017 to 2019). Persistent deficits in social interaction and communication and interaction as well as a markedly restricted repertoire of activity and interest as well as repetitive patterns of behavior. "Of these variants, 4 were found in genes not previously implicated in ASD nor listed in Autism databases (DDX26B, HTATSF1, ITIH6 and PLP1)." (PMID 28720891, 2017).
cognitive decline (2 papers, 2023). "Prior studies have found that PLP1 overexpression can lead to progressive leukodystrophy and cognitive decline." (PMID 37645701, 2023).
colon cancer (2 papers, 2020). "The TCGA results indicated that SPIB, KRT24, PHLPP2, PLP1, BEST4, CA7, and C11orf86 were all downregulated, while KRT80, SLC39A10, AJUBA, FOXQ1, and CLDN1 exhibited upregulated levels in colon cancer." (PMID 32633726, 2020).
dementia with Lewy bodies (2 papers, 2009 to 2017). "The abundance of SYNPO was lower whereas GSTP1 and PLP1 level were higher in Lewy body dementias and its clinical subtypes." (PMID 28800743, 2017). "On the other hand, VIM, PLP1 and GSTP1 failed to display significant alteration (p > 0.05) between control and either subtypes of Lewy body dementias." (PMID 28800743, 2017).